PABPC1 (poly(A) binding protein cytoplasmic 1)
Diseases named in the same sentence as PABPC1 in open-access papers (continued):
Sharing a sentence is not in itself a finding about the gene and the disease.
amyotrophic lateral sclerosis (3 papers, 2015 to 2024). Amyotrophic lateral sclerosis (ALS) is a neurodegenerative disease characterized by progressive muscular paralysis reflecting degeneration of motor neurons in the primary motor cortex, corticospinal tracts, brainstem and spinal cord. "The PABPC1 gene has been associated with the UBQLN2 gene, one of the key genes linked to amyotrophic lateral sclerosis (ALS)." (PMID 38540795, 2024).
colorectal cancer (3 papers, 2011 to 2023). A primary or metastatic malignant neoplasm that affects the colon or rectum. "Besides, abnormal changes and functions of PABPC1 were found in cervical cancer (CC), colorectal cancer, and gastric cancer." (PMID 32015336, 2020). "It is possible that HNRNPL, PABPC1, RPS4X, and RPS7 correlate with oxaliplatin resistance but are not directly involved biochemically in the process of resistance in colorectal cancer cell types." (PMID 22118625, 2011). "In addition, we identified several variants in genes not typically included in relevant gene panels for colorectal cancer, including CFTR, PABPC1 and TYRO3, which may be associated with an increased risk for cancer." (PMID 37296477, 2023).
COVID-19 (3 papers, 2020 to 2023). A disease caused by infection with severe acute respiratory syndrome coronavirus 2. "Of note, we observed numerous DTU genes involved in RNA splicing, with 10 genes (e.g. HNRNPC, SNRPD3, QKI, and LUC7L2) increased major transcript usage and 18 genes (e.g. SNRNP48, NCBP1, CELF2, RALY, and PABPC1) decreased major transcript usage in the COVID-19 patients." (PMID 35421082, 2022). "Similarly, PABPC1 and PABPC4 have been recently identified as downregulated COVID-19-altered proteins, both of which are known autoantigens, offering a possible explanation for the autoimmune complications observed in COVID-19 patients." (PMID 36835058, 2023).
duodenal cancer (3 papers, 2017 to 2024). "Similarly, in metastatic duodenal cancer, PABPC1 expression was upregulated in tumor cells, and overexpression of PABPC1 enhanced cell proliferative capacity, colony numbers and metastasis ability." (PMID 34027108, 2021).
neuroblastoma (3 papers, 2015 to 2021). Neuroblastoma (NB) is the most common solid, extracranial childhood tumor. "To better analyze the kinetics of SG assembly, we induced mild oxidative stress in the SH-SY5Y human neuroblastoma cell line with 50-μM arsenite and then visualized the formation of G3BP1- or PABPC1-positive SGs." (PMID 33362237, 2020).
pancreatic cancer (3 papers, 2024 to 2025). "PABPC1 was shown to promote cell proliferation and metastasis in pancreatic cancer." (PMID 39416165, 2024).
prostate tumors (3 papers, 2012 to 2023). "PABPC1 expression is significantly higher in prostate tumors than normal prostate tissue." (PMID 37956771, 2023).
Azoospermia (2 papers, 2024 to 2025). Absence of any measurable level of sperm,whereby spermatozoa cannot be observed even after centrifugation of the semen pellet. "In male reproduction, similar mutations could underlie cases of non-obstructive azoospermia characterized by meiotic arrest, as DAZL/PABPC1-dependent translation is crucial for spermatocyte survival." (PMID 41249172, 2025). "In addition, Oztuket al. reported that the expression of PABPC1 was decreased in testicular biopsy tissues from non-obstructive azoospermia patients, suggesting the critical role of PABPC1 in spermatogenesis." (PMID 39696987, 2024).
infertile (2 papers, 2021 to 2023). "Pabpc1 showed the highest expression level in the pachytene and round-spermatid (RS) stages, and its deficiency can cause infertility." (PMID 34312369, 2021). "Thus, our results showed a significant decrease in Pabpc1 protein level as compared to that in WT mice causing infertility because of Ubb-knockout, suggesting that this decrease in expression level may induce infertility along with changes in other protein levels." (PMID 34312369, 2021). "Importantly, PABPC1, PABPC1L, and PABPC3 expressions are perturbed in infertile men." (PMID 37176068, 2023).
melanoma (2 papers, 2017 to 2025). A malignant, usually aggressive tumor composed of atypical, neoplastic melanocytes. "This protein has a hypothesized, but still undefined, role at the mitochondria and our data indicate that high levels of PABPC1 expression in melanomas are associated with increased expression of genes encoding several mitochondrial proteins." (PMID 28484090, 2017). "Initially isolated and cloned from human melanoma cells, PABPC1 is evolutionarily conserved throughout eukaryotes." (PMID 40013670, 2025).
osteoarthritis (2 papers, 2023 to 2025). A noninflammatory degenerative joint disease occurring chiefly in older persons, characterized by degeneration of the articular cartilage, hypertrophy of bone at the margins and changes in the synovial membrane. "WDR11-AS1 expression is downregulated in osteoarthritic cartilage and inhibits inflammation-induced extracellular matrix (ECM) degradation by directly binding to PABPC1, highlighting its potential as a therapeutic target for osteoarthritis." (PMID 40969769, 2025).
acute kidney injury (1 paper, 2023). Sudden and sustained deterioration of the kidney function characterized by decreased glomerular filtration rate, increased serum creatinine or oliguria. "Five genes (CCT4, HSP90AA1, NCL, PABPC1, YBX1) were found to be associated with kidney disease, acute kidney injury, edema, tumor metastasis, transitional cell carcinoma, necrosis, and inflammation." (PMID 37058032, 2023). "CCT4, HSP90AA1, NCL, PABPC1, and YBX1 were found to be associated with kidney disease, acute kidney injury, edema, tumor metastasis, transitional cell carcinoma, necrosis, and inflammation." (PMID 37058032, 2023).
anaplastic large cell lymphoma (1 paper, 2023). Anaplastic large cell lymphoma (ALCL) is a rare and aggressive peripheral T-cell non-Hodgkin lymphoma, belonging to the group of CD30-positive lymphoproliferative disorders, which affects lymph nodes and extranodal sites. "Other FRK‐related fusion genes, including CAPRIN1::FRK, PABPC1::FRK, and MAPK9::FRK, have been identified in ALK‐negative anaplastic large cell lymphoma (ALCL)." (PMID 37601849, 2023).
Arrhythmia (1 paper, 2025). Any cardiac rhythm other than the normal sinus rhythm. "The negative correlation with PABPC1, involved in mRNA stability, suggested translational stress in arrhythmia-associated macrophages, further supported by concurrent HSPA6 upregulation." (PMID 40900730, 2025).
central precocious puberty (1 paper, 2021). "Here we reported that the three members of PABPs, including PABPC1, PABPC3 and PABPC4, were identified as novel substrates for MKRN3, whose deletion or loss-of-function mutations were genetically associated with human central precocious puberty (CPP)." (PMID 33744966, 2021).
cervical cancer (1 paper, 2022). A primary or metastatic malignant neoplasm involving the cervix. "This highlighted that PABPC4 specifically could impact the levels of hTERT mRNA, despite being expressed at less than 10% of the amount of PABPC1 in cervical cancer cell lines." (PMID 35891463, 2022). "Therefore, PABPC1 and PABPC4 were knocked down by shRNA in C33A cells, a cervical cancer cell line that does not contain HPV." (PMID 35891463, 2022).
developmental delay (1 paper, 2023). "Missense variants in PABPC1 have been reported in developmental disorders, but these variants are clustered in a different region of the gene and most affected patients had a much milder phenotype, characterised by moderate developmental delay but with achievement of ambulation in most cases." (PMID 37048120, 2023).
follicular thyroid cancer (1 paper, 2020). "Except for PABPC1, PABPC3 was also found as a cancer driver gene in follicular thyroid cancer." (PMID 32454908, 2020).
HCMV infection (1 paper, 2023). "Longer poly(A)‐tails on HCMV transcripts will permit binding of additional PABPC molecules, expected to promote the stability and translation of mRNAs, and is concordant with the upregulation of and dependence on PABPC1 in HCMV infection." (PMID 37846490, 2023).
inclusion body myositis (1 paper, 2013). A slowly progressive degenerative inflammatory disorder of skeletal muscles characterized by late onset weakness of specific muscles and distinctive histopathological features. "PABPC1 immuno-positive deposits forming conglomerates with poly A RNA were previously found in muscle biopsies of patients with sporadic inclusion body myositis (IBM) leading to the speculation that an autoantibody-mediated inhibition of mRNA degradation could play a role in the pathogenesis of IBM." (PMID 23483977, 2013).
ischemic stroke (1 paper, 2022). A stroke disorder caused by obstruction of blood flow to the brain, due to thrombotic (local blood clot formation) or embolic (due to a blood clot or other material traveling from another site) event. "Our findings suggest a close association of PABPC1, PFDN5, and TNF with female ischemic stroke patients." (PMID 35432523, 2022).
male infertility (1 paper, 2020). The inability of the male to effect fertilization of an ovum after a specified period of unprotected intercourse. "CFTR, mutations of which are associated with male infertility, might be coregulated by FXR1, HNRNPA1, MATR3, PABPC1, G3BP2, FMR1, and SRSF7." (PMID 32316190, 2020).
oral cancer (1 paper, 2020). "PABPC1 is located at chromosome region 8q22.3, and the loss of heterozygosity at this region is associated with occurrence of oral cancer and breast cancer." (PMID 32015336, 2020).
pancreatic adenocarcinoma (1 paper, 2023). "However, the effects of PABPC1 expression in pancreatic adenocarcinoma (PAAD) have not been investigated." (PMID 37506150, 2023).
thyroid cancer (1 paper, 2025). "This approach identified significant dependencies on key genes/proteins such as KRAS, NRAS, PABPC1, PPP2R1A, STAG2, and BRAF in thyroid cancer cell lines, underscoring their potential as critical therapeutic targets." (PMID 40297138, 2025).
triple-negative breast carcinoma (1 paper, 2022). An invasive breast carcinoma which is negative for expression of estrogen receptor (ER), progesterone receptor (PR), and human epidermal growth factor receptor 2 (HER2). "Furthermore, triple-negative breast cancer patients face resistance to the drug trastuzumab by the active involvement of Polyadenylate-binding protein 1 (Pabpc1), expression of which is induced by overexpression of SNHG1463." (PMID 36151122, 2022).
venereal disease (1 paper, 2025). "Including healthy controls with no history of tobacco or alcohol use, penile lesions, or venereal disease allowed for the identification of shared mutations (PABPC1, MUC16, and KAT6B) between groups." (PMID 40486961, 2025).
Wilms tumor (1 paper, 2023). An embryonal neoplasm characterized by the presence of epithelial, mesenchymal, and blastema components. "We found that core genes (CCT4, HSP90AA1, NCL, PABPC1, YBX1) were lowly expressed in tumor tissue samples and highly expressed in standard tissue samples, which may have reverse regulatory significance for Wilms tumor." (PMID 37058032, 2023).
cancer (53 papers, 2007 to 2025). A tumor composed of atypical neoplastic, often pleomorphic cells that invade other tissues. "For P11, there were two nonsynonymous mutations (USP6 and PABPC1) shared by two tumors, both of which were cancer-related mutations." (PMID 35171361, 2022). "Although mutations in PABPC1 were also detected in all control individuals, the mutation types differed: frameshift mutations were found in controls, while non-synonymous mutations were predominant in cancer patients." (PMID 40486961, 2025). "PABPC1 (poly (A) binding protein cytoplasmic 1) is an important component of the RNA stabilization protein complex involved in germ cell development and mRNA translational regulation, and they have been linked to cancer." (PMID 35432523, 2022). "Additionally, considering different cancer-derived mutations for the PABPC1 protein, we presented an overview of different hotspots, along with measuring the change in stability of the structure upon inserting point mutations." (PMID 36428549, 2022). "PABPC1 is a key driver of multiple cancer hallmarks in various cancers, such as angiogenesis and invasion." (PMID 40869298, 2025). "Second, we uncover the following important genes: KIF18A, CCDC19, and PABPC1, which are consistent with previous cancer studies." (PMID 39416165, 2024). "Currently, the role of PABPC1 expression is primarily researched in cancer, neurodegenerative diseases, cardiovascular diseases, and spermatogenesis disorders." (PMID 37506150, 2023). "Abnormal changes and functions of PABPC1 have been reported in cancers and the cellular stress response." (PMID 36614257, 2023). "In our research, KEGG analysis revealed that these DEGs regulated by PABPC1 were enriched in various cancer‐related pathways, which also included the IL‐17 signaling pathway and focal adhesion." (PMID 37506150, 2023). "The expression of cytoplasmic poly (A) binding protein‐1 (PABPC1) has been reported in multiple cancer types." (PMID 37506150, 2023). "Lastly, we examined the impact of the expression of ENO1, MSN, Mtdh, and PABPC1 on the survival rate of cancer patients." (PMID 36923539, 2023). "For miRNA-targeted genes, PABPC1 increases the efficiency of miRNA repression, and this efficiency is higher in cancer cells than in normal cells." (PMID 36531055, 2022). "Despite the key role of PABPC1 in cancer progression, the mechanism by which it is regulated and participates in ESCC has not been clearly elucidated." (PMID 35346324, 2022). "Molecular details from this study will provide a detailed understanding of the PABPC1 structure, which can be used to modulate the activity of this gene, resulting in production of mutant peptide or neoantigens in cancer." (PMID 36428549, 2022). "Considering that the EMT is frequently used to explain how cancer cells acquire aggressiveness, we investigated the action of PABPC1 on the EMT-related markers using Western blot analysis." (PMID 34027108, 2021). "In the NDRG1 module, PSMD2 is overexpressed in many cancer cells, whereas PABPC1, EIF4G1, EIF3H, EIF3E, and EIF3K are RNA translational control members." (PMID 26735889, 2016). "PABPC1 selectively regulates gene expression through interacting with long non-coding RNAs (lncRNAs) and miRNAs that increase cancer cell plasticity and promote cancer progression." (PMID 41357316, 2025). "Notably, proteins enriched in CM included Moesin (MSN), Enolase 1 (ENO1), and polyA-binding protein 1 (PABPC1), which are considered tumorigenic in many types of cancer." (PMID 36923539, 2023). "However, the mechanisms by which PABPC1 promotes tumorigenesis in different cancer types are diverse." (PMID 35346324, 2022).
cancer (continued). "EIF4G2 and PABPC1 may be involved in the progression of cancer by affecting translational initiation, while SOD1 and ATP5H may participate in carcinogenesis via influencing oxidative stress and oxidative phosphorylation." (PMID 30863671, 2019). "Notably, for all the seven HUB nodes of the linking region between three cancer networks, mutations were found in all three cancers (BlC, KiC, PrC) with the higher frequency percentages identified for four nodes: MAP3K7, NR3C1, PABPC1 and CTNNB1." (PMID 29991691, 2018). "One sub-network (network index 8) includes two cancer genes PABPC1, GIGYF2." (PMID 28415609, 2017). "However, the mechanisms underlying the increased PABPC1 expression in cancer has not yet been clearly demonstrated." (PMID 35346324, 2022). "Both PABPC1 and OPA1 are aberrantly expressed in many cancers and are known to promote tumorigenesis and progression, thereby serving as promising candidates to target in RBness cancers." (PMID 40138429, 2025). "Second, we uncover the following important genes: KIF18A, PABPC1, and SPIC, which are consistent with previous cancer studies." (PMID 40286292, 2025). "Poly(A)-binding protein, cytoplasmic 1 (PABPC1), is an extensively studied protein, and recent research has revealed its involvement in the tumorigenesis of numerous cancers." (PMID 39048965, 2024). "Mechanistically, exosomal circPLEKHM1 promoted PABPC1-eIF4G interaction to facilitate the translation of the oncostatin M receptor (OSMR), thereby promoting macrophage polarization for cancer metastasis." (PMID 38509870, 2024). "Intriguingly, our analysis identified proteins known as main stress granule markers (G3BP1, PABPC1, and TIA1) in ascitic fluids and secretomes of cancer cells after chemotherapy." (PMID 38898005, 2024). "PABPC1 and collagen type XII α1 chain (COL12A1) expression in PAAD and their role in tumor prognosis and tumor stage were investigated using The Cancer Genome Atlas database analysis." (PMID 37506150, 2023). "Paradoxically, CM was enriched with PABPC1, ENO1, and MSN, all of which have been considered oncogenic since their elevated transcript levels in cancer tissues significantly reduce the survival rate." (PMID 36923539, 2023). "The prognostic signature that we constructed consisted of seven cancer driver genes (CDKN2C, HRAS, IRAK1, LOX, MYCN, NRAS, and PABPC1)." (PMID 36017503, 2022). "Most of these APA regulators were specifically upregulated in seven cancer types, while PPP1CB, PCF11, and PABPC1 were significantly downregulated in ESCC." (PMID 35654793, 2022). "In our study, we found that most cancer driver genes are specifically expressed in tumor tissue, and we constructed a four-mRNA prognostic signature (ETV5, EZH2, PABPC1, ZCRB1) that has higher predictive power than other clinical features." (PMID 34335239, 2021). "Of the eight modeling RBPs, half were upregulated including PABPC1, PRPF6, OAS1, IPO7, and half were downregulated including RBM5, RBM6, LSM12, and FXR7 in cancer cases." (PMID 33584809, 2020). "To find a possible link between these three cancers subjected to arsenicals exposure, we merged the three networks and identified seven HUB nodes (RXRA, MAP3K7, NR3C1, PABPC1, NDRG1, RELA and CTNNB1) of the linking region between three cancer networks." (PMID 29991691, 2018). "We focused on PABPC1 that gave the most significant negative effect on the survival rate of all cancer patients (p = 1.1x10-16) and the second-strongest anti-tumor capability next to SNRPE." (PMID 36923539, 2023). "For miRNA non-target genes, PABPC1 interacted with eIF4G to inhibit the decay of mRNA, making translation higher in cancer cells than in normal cells and thus increasing cellular activity." (PMID 36531055, 2022).
cancer (continued). "PABPC1 selectively regulates transcripts by interacting with non-coding RNAs such as long-stranded non-coding RNAs, microRNAs specific translation and expression of specific oncogenic proteomes, enhancing cancer cell plasticity and thus promoting therapeutic evasion of cancer progression." (PMID 36531055, 2022).